RPL18A (ribosomal protein L18a)
Description:
Component of the large ribosomal subunit. The ribosome is a large ribonucleoprotein complex responsible for the synthesis of proteins in the cell.
Synonyms: L18A; eL20
Tractability: Small molecule: an approved drug acts on it; a structure with a bound ligand is known; a high-quality ligand is known. PROTAC: UniProt records ubiquitination sites on it; ubiquitination databases record sites on it; its protein half-life has been measured; a small molecule that binds it is known. Other modalities: a drug acting on it is in phase 2 or 3 trials.
Target class: Other cytosolic protein
Gene: Protein-coding gene on chromosome 19 (17,859,868 to 17,864,153, forward strand). Ensembl gene ENSG00000105640.
Subcellular location: Cytoplasm
Subcellular location (Human Protein Atlas): Nucleoli; Cytosol; Nucleoplasm
Pathways (Reactome):
Metabolism of proteins: Eukaryotic Translation Termination; Formation of a pool of free 40S subunits; GTP hydrolysis and joining of the 60S ribosomal subunit; L13a-mediated translational silencing of Ceruloplasmin expression; PELO:HBS1L and ABCE1 dissociate a ribosome on a non-stop mRNA; Peptide chain elongation; Ribosome Quality Control (RQC) complex extracts and degrades nascent peptide; SRP-dependent cotranslational protein targeting to membrane; ZNF598 and the Ribosome-associated Quality Trigger (RQT) complex dissociate a ribosome stalled on a no-go mRNA
Metabolism of RNA: Major pathway of rRNA processing in the nucleolus and cytosol; Nonsense Mediated Decay (NMD) enhanced by the Exon Junction Complex (EJC); Nonsense Mediated Decay (NMD) independent of the Exon Junction Complex (EJC)
Cellular responses to stimuli: Response of EIF2AK4 (GCN2) to amino acid deficiency
Developmental Biology: Regulation of expression of SLITs and ROBOs
Disease: Viral mRNA Translation
Metabolism: Selenocysteine synthesis
Gene Ontology:
Molecular function: protein binding; RNA binding; structural constituent of ribosome
Biological process: cytoplasmic translation; negative regulation of myoblast fusion; spermatogenesis; striated muscle contraction; translation
Cellular component: cytoplasm; cytosolic large ribosomal subunit; cytosolic ribosome; membrane; cytosol; postsynaptic density; ribosome
Genetic constraint (gnomAD): Loss-of-function variants: 0 observed, 20.77 expected, observed/expected ratio (o/e) 0, 90% interval 0 to 0.14. The upper end of that interval is the gene's LOEUF score, 0.14, which puts it in group 1 of 6, group 1 being the genes least tolerant of losing a copy. Missense variants: 148 observed, 226.22 expected, observed/expected ratio (o/e) 0.65, 90% interval 0.57 to 0.75. Synonymous variants: 114 observed, 90.31 expected, observed/expected ratio (o/e) 1.26, 90% interval 1.08 to 1.48.
Homologues: Orthologues: dog RPL18A (99% identical), mouse Rpl18a (99% identical), rat Rpl18a (98% identical), rat AABR07001902.1 (93% identical), tropical clawed frog rpl18a (93% identical), zebrafish rpl18a (91% identical), rabbit RPL18A (87% identical), macaque RPL18A (82% identical), Drosophila melanogaster RpL18A (70% identical), Caenorhabditis elegans rpl-20 (62% identical).
Diseases named in the same sentence as RPL18A in open-access papers:
RPL18A is named in the same sentence as 23 diseases in open-access papers, as found by Europe PMC text mining. Sharing a sentence is not in itself a finding about the gene and the disease. The quoted sentences say what the papers report.
endometriosis (2 papers, 2022 to 2023). The growth of functional endometrial tissue in anatomic sites outside the uterine body. "Additionally, RPL18A is identified as a differentially expressed gene in infertile endometriosis." (PMID 38012716, 2023).
infertile (2 papers, 2022 to 2023). "The topological analysis of the WGCN of the testis transcriptional cell atlas highlighted important somatic genes in this network, including RPL39, RPL10, RPL13A, FTH1, RPS2, and RPL18A, which have been reported to be associated with infertility." (PMID 38012716, 2023).
acute myeloid leukemia (1 paper, 2022). Acute myeloid leukemia (AML) is a group of neoplasms arising from precursor cells committed to the myeloid cell-line differentiation. "Further, an in-depth literature analysis revealed that several of these genes play important roles in cancer (CDCA3, ECEL1, EN1, HLA-DMB, SPRR2A, TMEM40) including acute myeloid leukemia (CDCA3, HLA-DMB, RPL18A, PF4, PRG3) and T cell acute lymphoblastic leukemia (TLX3)." (PMID 35008420, 2022).
breast carcinoma (1 paper, 2025). "The variant was uncovered during routine germline genetic testing in a breast cancer patient and genotyped as a complete processed RPL18A transcript inserted into the coding region of the BRCA1 gene." (PMID 41375073, 2025).
colon cancer (1 paper, 2023). "Among the ribosomal proteins that we observed to be associated with our EC samples, RPS18 and RPL18A have been previously reported in association with colon cancer and RPS14 and RPS18 in prostate cancer." (PMID 37760635, 2023).
gastric cancer (1 paper, 2016). A primary or metastatic malignant neoplasm involving the stomach. "Functional analysis of TRIM28, EIF4A2, NAP1L1, PLD3, RPL18A, and TRPM7 suggested that they play direct roles in gastric cancer." (PMID 27835598, 2016).
glioma (1 paper, 2024). A benign or malignant brain and spinal cord tumor that arises from glial cells (astrocytes, oligodendrocytes, ependymal cells). "In our study, the overexpression of RPs, such as RPSA, RPL18A, RPL19, and RPS12, was associated with a better prognosis in patients with glioma." (PMID 38672212, 2024). "The higher expression of BMP2, RPL18A, RPL19, and RPS12 is associated with better outcomes in patients with glioma." (PMID 38672212, 2024). "Of these additional genes, the higher expression of four genes (BMP2, RPL18A, RPL19, and RPS12) was also significantly associated with better survival and delayed tumor recurrence in patients with glioma, especially those with grade III glioma." (PMID 38672212, 2024). "However, the RPs (RPL18A, RPL19, and RPS12) showed a more distinct trend, which was statistically significant for both OS and PFS only in grade III gliomas." (PMID 38672212, 2024).
leukemia (1 paper, 2022). A malignant (clonal) hematologic disorder, involving hematopoietic stem cells and characterized by the presence of primitive or atypical myeloid or lymphoid cells in the bone marrow and the blood. "Importantly, some of these genes have already been reported in relation to CML (e.g., AURKB, AZU1, HLA-B, HLA-DMB, PF4) and others have been found to play important roles in different leukemias (e.g., CDCA3, RPL18A, PRG3, TLX3)." (PMID 35008420, 2022).
male infertility (1 paper, 2023). The inability of the male to effect fertilization of an ovum after a specified period of unprotected intercourse. "We also identified key somatic cell genes, including RPL39, RPL10, RPL13A, FTH1, RPS2, and RPL18A, which were highly influential in the weighted gene co-expression network of the testis transcriptional cell atlas and have been previously implicated in male infertility." (PMID 38012716, 2023).
melanoma (1 paper, 2021). A malignant, usually aggressive tumor composed of atypical, neoplastic melanocytes. "Patients with melanoma with hotspot mutations in RPL18A promoter have significantly poorer prognoses compared with patients without those hotspot mutations." (PMID 33851100, 2021).
schizophrenia (1 paper, 2015). A major psychotic disorder characterized by abnormalities in the perception or expression of reality. "This analysis demonstrated that the levels of eIF2α, RPL13, RPL13A, RPL18A, RPL27A and RPL32 were reduced in schizophrenia patient-derived cells in comparison with controls." (PMID 26485547, 2015).
tumor (5 papers, 2015 to 2024). "On the counterpart, 40435_at (SLC25A6), 33614_at (RPL18A, RPL18AP3), and 1657_at (PTPRR) are down-regulated (high expression values in normal class and low expression values in tumor class)." (PMID 33375940, 2020).
cancer (3 papers, 2020 to 2025). A tumor composed of atypical neoplastic, often pleomorphic cells that invade other tissues. "These included RPL6, RPL7, RPL18A, RPS2, EIF3E, EIF3J, and UBA52, reflecting the elevated protein synthesis demands of cancer cells." (PMID 41228302, 2025).
infection (2 papers, 2018 to 2025). The state of being infected such as from the introduction of a foreign agent such as serum, vaccine, antigenic substance or organism. "A few genes identified during the IgG peak such as IFI27 (up-regulation), S-formylglutathione hydrolase (up-regulation) and Ribosomal Protein L18a (down-regulated) seem to be regulated in a manner to potentially confer a degree of protection from the sequential infection in BALB/c mice." (PMID 30279404, 2018). "Previous studies comparing untreated HIV-infected individuals to healthy controls reported decreased expression of several ribosomal proteins, such as RPS27, RPL18A, RPL8, RPL26, RPL4, and RPS21, possibly reflecting impaired translational activity during active infection." (PMID 41226717, 2025).
infectious disease (1 paper, 2024). A disorder directly resulting from the presence and activity of a microbial, viral, or parasitic agent in humans. "Overrepresentation analyses of upregulated proteins yielded six Reactome pathways enriched, highlighting “HSA-5663205: Infectious disease” (strength = 1.19; FDR = 0.003), which included the proteins RPL18A, PSMA5, HSPA1B, RPL35A, and ISG15." (PMID 39409176, 2024).
RPL18A also shares sentences with these, for which no sentence is quoted: colon adenocarcinoma (1 paper); COVID-19 (1); heart failure (1); macrosomia (1); non-small cell lung carcinoma (1); prostate carcinoma (1); ventricular tachycardia (1); virus infections (1).